RFX1 (regulatory factor X1)
Diseases named in the same sentence as RFX1 in open-access papers (continued):
Sharing a sentence is not in itself a finding about the gene and the disease.
Colon Cancer (2 papers, 2012 to 2025). "In short, RFX1 is higher in digestive tract cancers and linked to worse prognosis in colon cancer, highlighting its potential as a prognostic marker." (PMID 41425715, 2025). "To further elucidate the role of RFX1 in immunotherapy, we first evaluated the association between RFX1 and common immune checkpoint inhibitors in colon cancer." (PMID 41425715, 2025). "We classified colon cancers into subgroups with high and low RFX1 expression and characterized their immune profiles, mutational profiles, tumor immunotherapy and drug sensitivity." (PMID 41425715, 2025). "We classified colon cancers into subgroups with high and low RFX1 expression and characterized their immune profiles, mutational profiles, cancer immunotherapy and drug sensitivity." (PMID 41425715, 2025). "The plastic role of regulatory factor X1 (RFX1) in colon cancer progression and its impact on the tumor microenvironment remain poorly understood." (PMID 41425715, 2025). "The results showed that PDCD1LG2, ICOS, CD86, CD80, CD48, and CD274 showed a significant exclusion situation from RFX1 expression in colon cancer." (PMID 41425715, 2025). "The differential pan-cancer expression of RFX1 prompted us to explore its prognostic value in digestive tract tumors, particularly colon cancer." (PMID 41425715, 2025). "In contrast, CD27, CD276, LAG3, LGALS9, PDCD1, and TMIGD2 showed a highly enriched trend of expression with RFX1 in colon cancer." (PMID 41425715, 2025). "Further, we characterized the correlation between immune checkpoint-related genes and RFX1 in colon cancer." (PMID 41425715, 2025). "We characterized the immune landscape, mutational features, shaping inflammatory features, immunotherapy and drug sensitivity of RFX1 in colon cancer." (PMID 41425715, 2025). "These tools provide complementary perspectives, and further validation in immunotherapy-treated colon cancer cohorts is needed to confirm the predictive relevance of RFX1." (PMID 41425715, 2025). "We have gradually focused our attention from pan-cancer to the molecular characterization of RFX1 in colon cancer." (PMID 41425715, 2025). "In colon cancer, RFX1 expression was mainly negatively correlated with chemokine-associated immunokines, such as CXCL10 and CXCL11." (PMID 41425715, 2025). "Undeniably, as an oncogene, RFX1 is highly expressed in colon cancer and has significant prognostic value." (PMID 41425715, 2025). "In addition, we not only elucidated the expression and prognostic value of RFX1 in colon cancer using multi-omics analysis, but also innovatively introduced persistent tumor mutational burden (pTMB) as a co-stratification tool." (PMID 41425715, 2025). "Collectively, these findings raise the hypothesis that RFX1 acts as an oncogenic transcription factor in colon cancer by shaping an immunosuppressive microenvironment, modulating mutational dynamics, and conferring resistance to immunotherapy." (PMID 41425715, 2025). "Our aim is to determine whether RFX1 can serve as a predictive biomarker and potential target in the immunogenomic stratification of colon cancer." (PMID 41425715, 2025). "The study aimed to clarify the molecular and clinical role of RFX1 in colon cancer." (PMID 41425715, 2025). "The study of RFX1 in colon cancer is still in the preliminary stage, especially transcriptional regulation and epigenetic modifications, which may determine its pleiotropic characteristics." (PMID 41425715, 2025). "In colon cancer, type 2 T helper cells and activated CD4 T cells were highly negatively correlated with RFX1." (PMID 41425715, 2025). "Previously, we found that in colon cancer, RFX1 showed a negative trend in correlation with the expression of key chemokines (CXCL9 and CXCL10) that induce the recruitment of CD8+ T cells to the tumor microenvironment." (PMID 41425715, 2025). "On the contrary, colon cancer patients with high RFX1 expression may not be suitable for implementing immune checkpoint inhibitor therapy." (PMID 41425715, 2025).
esophageal adenocarcinoma (2 papers, 2011 to 2019). A malignant tumor with glandular differentiation arising predominantly from Barrett mucosa in the lower third of the esophagus. "Given these extensive activities of Rfx1 in cell growth and oncogenesis, our discovery of the gradual loss of Rfx1 expression in the progression to esophageal adenocarcinoma suggests that the factor has a functional role in that context." (PMID 21935353, 2011). "Thus, we conclude that Rfx1 expression in the esophageal epithelium is very frequently lost during the progression to esophageal adenocarcinoma, and its loss appears to be a more reliable marker of cancer progression than the up-regulation and then down-regulation of Cdx2." (PMID 21935353, 2011). "By contrast, in samples of Barrett's esophagus with dysplasia, we found a more marked, statistically significant decrease in the percentage of Rfx1 positive nuclei in epithelial cells (p ≤0.0001), whereas the stromal cells retained Rfx1 expression." (PMID 21935353, 2011). "Since we found that Rfx1 is a negative regulator of the Cdx2 +7 element, we wanted to determine if Rfx1 levels change during the progression from normal human esophageal mucosa to the development of esophageal adenocarcinoma." (PMID 21935353, 2011). "Our approach revealed that Rfx1 expression decreases gradually during cellular progression to esophageal adenocarcinoma, indicating that mechanistic and clinically useful insights can emerge from studies of transcription factors bound to silent genes." (PMID 21935353, 2011). "We observed a marked and statistically significant decrease in the levels of Rfx1 expression in Barrett's esophagus with dysplasia and in esophageal adenocarcinoma." (PMID 21935353, 2011). "Taken together with our observation that there is a marked decrease of Rfx1 expression in the epithelium of Barrett's esophagus with dysplasia, our findings suggest that Rfx1 helps control the maintenance of the squamous epithelial cell identity in the esophagus and hence antagonizes dysplasia." (PMID 21935353, 2011). "By screening numerous staged samples of human tissues, we show that Rfx1 expression is extinguished during the progression to esophageal adenocarcinoma and thus may serve as a marker of cancer progression." (PMID 21935353, 2011). "Considering the poor clinical prognosis of esophageal adenocarcinoma, Rfx1 down-regulation during progression to adenocarcinoma may be a useful new marker of cancer development." (PMID 21935353, 2011). "In Barrett's esophagus, comparing expression from 11 samples, there was a qualitative but not statistically significant decrease in the percentage of Rfx1 positive nuclei in comparison to normal samples (p≤0.12) (“E”, arrows)." (PMID 21935353, 2011).
lung adenocarcinoma (2 papers, 2021 to 2025). A carcinoma that arises from the lung and is characterized by the presence of malignant glandular epithelial cells. "In contrast, RFX1 expression was low in cancers such as cervical squamous cell carcinoma and lung adenocarcinoma." (PMID 41425715, 2025). "On the contrary, weighted gene co-expression network analysis (WGCNA) of lung adenocarcinoma samples designated RFX1 as an enriched transcription factor in microtubule processing and tumor development, which needs further validation." (PMID 33964962, 2021).
ovarian carcinoma (2 papers, 2018 to 2021). A malignant neoplasm originating from the surface ovarian epithelium. "FGF1, a target that RFX1 negatively regulates, plays a significant role in conferring platinum drug resistance and ovarian cancer progression." (PMID 33964962, 2021). "Though in the majority of cases, RFX1 acts as a negative regulator of metastasis, it has been reported that the transcriptional activity of RFX1 was doubled in a metastatic ovarian cancer cell line HO-8910PM compared to its parent cell line, suggesting a positive role of RFX1 in cancer metastasis." (PMID 33964962, 2021).
acute lymphoblastic leukemia (1 paper, 2021). Leukemia with an acute onset, characterized by the presence of lymphoblasts in the bone marrow and the peripheral blood. "RFX1 is also reported to interact with an intracellular active form of NOTCH-1 (ICN1) in human T-cell acute lymphoblastic leukemia (T-ALL) cells." (PMID 33964962, 2021).
acute myeloid leukaemia (1 paper, 2025). "However, in a few carcinomas, mainly represented by pancreatic cancer and acute myeloid leukaemia, RFX1 showed a highly positive correlation with the infiltration of each immune cell, with a tendency of significant enrichment." (PMID 41425715, 2025).
Alstrom syndrome (1 paper, 2018). A multisystemic disorder characterized by cone-rod dystrophy, hearing loss, obesity, insulin resistance and hyperinsulinemia, type 2 diabetes mellitus, dilated cardiomyopathy (DCM), and progressive hepatic and renal dysfunction. "RFX1 controls ALMS1 gene expression by binding to X-boxes, and mutation of ALMS1 causes Alstrom syndrome, a primary ciliopathy." (PMID 29298325, 2018).
Arthritis (1 paper, 2018). Inflammation of a joint. "In addition, we also found that RFX1 expression level was negatively correlated with serum C-reactive protein (CRP) level, a surrogate marker of IL-6 activity, in SLE patients with active arthritis." (PMID 29422534, 2018).
asthma (1 paper, 2025). "The results identified MEblack as a cluster containing 741 asthma-related core genes, including POMP, GUSBL2, RBM39, PSMA6, RFX1, TCEB1, PSMD6, and others." (PMID 41403444, 2025).
bladder cancer (1 paper, 2025). "The results showed that RFX1 showed a negative correlation with the infiltration of immune cells in most of the tumors, such as bladder cancer and sarcoma." (PMID 41425715, 2025).
brain tumors (1 paper, 2019). "Rfx1 has an important function in brain tumors and sensorineural hearing loss." (PMID 31791390, 2019).
breast tumor (1 paper, 2023). "In addition, several papers have reported aberrant gene body methylation, including introns in cancer, e.g., hypermethylation of EGFR, LHX2, SOX9, and RFX1 introns in breast tumor tissue compared to paired adjacent tissue." (PMID 37296582, 2023).
colitis (1 paper, 2023). Inflammation of the colon. "We found that the relative mRNA expression of Rfx1 and M1 macrophage–related genes Il6, Tnf, and Il1b were significantly increased in the colon tissue of mice with colitis compared with the control group." (PMID 37733446, 2023). "RFX1 KO alleviated DSS-induced colitis and promoted tumor development." (PMID 37733446, 2023). "For detecting the effect of Rfx1 on M1 macrophage polarization in vivo, we induced WT and CKO mice with colitis induced by DSS." (PMID 37733446, 2023).
colorectal cancer (1 paper, 2025). A primary or metastatic malignant neoplasm that affects the colon or rectum. "In order to delve deeper into the clinical implications of RFX1 in the context of colorectal cancer, we conducted an immunohistochemical analysis using a colorectal cancer tissue microarray comprising 119 pairs of colorectal cancer and normal tissue samples." (PMID 41425715, 2025). "While our study provides substantial insights into the immunogenomic and prognostic role of RFX1 in colorectal cancer, several limitations remain." (PMID 41425715, 2025). "Transitioning back to the clinical aspect of our study, we conducted an assessment of RFX1 expression in colorectal cancer and embarked on an exploration of its clinical relevance and significance." (PMID 41425715, 2025). "To further validate the effect of RFX1 on colorectal cancer proliferation in vitro, we constructed another stable line overexpressing RFX1 in HCT-116 cell line." (PMID 41425715, 2025). "Through the application of qPCR to 14 pairs of colorectal cancer tissues and their respective normal tissue counterparts, we noted a substantial elevation in RFX1 mRNA expression levels within the colorectal cancer samples when juxtaposed with the normal tissues (p = 0.0034)." (PMID 41425715, 2025). "Furthermore, Kaplan-Meier analyses unveiled that elevated levels of RFX1 expression served as an indicator of unfavorable prognosis in colorectal cancer." (PMID 41425715, 2025). "Consistent findings were subsequently replicated through western blot analysis, where 10 pairs of colorectal cancer tissue specimens and their corresponding normal tissue counterparts demonstrated a parallel increase in RFX1 protein expression levels (p = 0.0136)." (PMID 41425715, 2025). "Specifically, establishing RFX1 knockdown or overexpression models in colorectal cancer cell lines, followed by co-culture with immune cells such as CD8+ T cells or macrophages and performing immune phenotyping, could help clarify its regulatory effects on immune cell recruitment and activation." (PMID 41425715, 2025).
coronary atherosclerosis (1 paper, 2025). Atherosclerosis of the coronary vasculature. "In patients with coronary atherosclerosis, deletion of RFX1 activates TLR4 and is involved in disease progression through histone modifications that further activate CD14+ monocytes." (PMID 41425715, 2025).
deafness (1 paper, 2019). An inherited or acquired condition characterized by the complete loss of the ability to hear from one or both ears. "In Rfx1/3 conditional knockout mice, the rapid loss of initially well-formed outer hair cells induced secondary deafness, which indicates an essential role for RFX1 in hearing." (PMID 30857550, 2019).
dementia (1 paper, 2022). Loss of intellectual abilities interfering with an individual's social and occupational functions. "In contrast, by binding to the regulatory factor X1 (RFX1) mRNA, miR-124 could increase the expression of RFX1, resulting in the suppression of apolipoprotein E (APOE) and cellular amyloid beta (Aβ) in microglia, which could undermine the cognitive behavior of dementia." (PMID 35592472, 2022).
diabetes (1 paper, 2022). "TF Rfx1is playing downstream role on signal transducer and activator of transcription 3 (STAT3) pathway while the expression of Rfx1 is regulated by interleukin-6 (IL-6)-STAT3 signaling pathway, and STAT3 plays an important role in diabetes pathogenesis." (PMID 36037214, 2022).
dysplasia (1 paper, 2011). A usually neoplastic transformation of the cell, associated with altered architectural tissue patterns. "By contrast, we find that Rfx1 expression in the esophageal epithelium becomes gradually extinguished during progression to cancer, i.e, expression of Rfx1 decreased markedly in dysplasia and adenocarcinoma." (PMID 21935353, 2011).
experimental autoimmune encephalomyelitis (1 paper, 2018). An autoimmune demyelinating disease of the central nervous system that is produced experimentally in animals by the injection of homogenized brain or spinal cord in Freund's adjuvant. "Conditional deletion of Rfx1 in mice exacerbates experimental autoimmune encephalomyelitis and pristane-induced lupus-like syndrome and increases induction of Th17 cells." (PMID 29422534, 2018).
head and neck cancer (1 paper, 2021). A primary or metastatic malignant neoplasm affecting the head and neck. "RFX1 also suppresses MCP1 transcription, which is known to induce EMT in head and neck cancers through AKT/STAT3/SNAIL signaling." (PMID 33964962, 2021). "RFX1 knockout led to decreased HDAC1 and SUV39H1 recruitment to the MCP1 promoter, increasing its expression, which on the other hand, promotes EMT and cell migration in MCF-7 and OML1 (human head and neck cancer cell line)." (PMID 33964962, 2021).
Hepatic steatosis (1 paper, 2018). Steatosis is a term used to denote lipid accumulation within hepatocytes. "Among these genes, RFX1 was investigated further because its activity can be regulated by a hepatic steatosis/lipid metabolism-associated factor, retinoic acid (an active metabolite of vitamin A that has been implicated in the regulation of lipid metabolism and hepatic steatosis in animal models)." (PMID 30400792, 2018).
insulinoma (1 paper, 2019). "Involvement of RFX proteins is supported by ChIP-Seq data from other studies, for example for murine Rfx1 and Rfx3 in neural progenitors and Min6 insulinoma cells, respectively (data accessed via the Cistrome Data Browser)." (PMID 30421101, 2019).
lupus erythematosus (1 paper, 2025). An autoimmune, connective tissue chronic inflammatory disorder affecting the skin, joints, kidneys, lungs, heart, and the peripheral blood cells. "Therefore, increased RFX1 expression is favorable for reducing the progression of lupus erythematosus by inhibiting T cell reactivity." (PMID 41425715, 2025).
neuroblastoma (1 paper, 2016). Neuroblastoma (NB) is the most common solid, extracranial childhood tumor. "Some of these transcription factor complexes have been implicated in neuroblastoma tumorigenesis, including E2F, PAX5, and RFX1." (PMID 27732954, 2016).